IQGAP3 (IQ motif containing GTPase activating protein 3)
Diseases named in the same sentence as IQGAP3 in open-access papers (continued):
Sharing a sentence is not in itself a finding about the gene and the disease.
cancer (continued). "This study evaluated the potential role of IQGAP3 and clinical significance in pan-cancer through combined multiomics analysis." (PMID 36164370, 2022). "We also showed that IQGAP3 expression was positively correlated with sensitivity to different types of drugs in the Genomics of Drug Sensitivity in Cancer (GDSC) database." (PMID 35274003, 2022). "Next, we explored the relationship between IQGAP3 expression and immune cell infiltration in different cancer types." (PMID 35274003, 2022). "Collectively, these data indicated that IQGAP3 expression was closely related to the prognosis of patients with different cancer types." (PMID 35274003, 2022). "IQGAP3 expression was positively correlated with 38 types of immune cells in 27 cancer types and negatively correlated with 38 types of immune cells in one cancer type." (PMID 35274003, 2022). "Survival analyses showed that a low DNA-methylation level of IQGAP3 was correlated with the better poor prognosis in diverse cancer." (PMID 35274003, 2022). "The DNA methylation of IQGAP3 was highly and negatively correlated with IQGAP3 expression in diverse cancer types." (PMID 35274003, 2022). "We showed above that a high expression of IQGAP3 was correlated with the prognosis of patients with different cancer types." (PMID 35274003, 2022). "Overall, these results showed that IQGAP3 expression was upregulated in different types of human cancer." (PMID 35274003, 2022). "We found that IQGAP3 expression was significantly associated with TMB and MSI in diverse cancer types." (PMID 35274003, 2022). "Collectively, our findings revealed that the IQGAP3AR/let-7c-5p axis–mediated upregulation of IQGAP3 expression promoted cancer progression and immune cell infiltration in different types of human cancer." (PMID 35274003, 2022). "We also examined if the methylation level of IQGAP3 affected the prognosis of patients with different types of cancer." (PMID 35274003, 2022). "For example, IQGAP3 was investigated and expected to serve as an effective prognostic biomarker for pan-cancer immune-related therapy." (PMID 36430577, 2022). "Although the exact function of IQGAP3 remains largely unexplored, its aberrant expression has been reported in several types of cancers." (PMID 34638508, 2021). "In conclusion, like IQGAP1, a known oncogene that is overexpressed in various cancer types, IQGAP3 also has important roles in carcinogenesis, especially in cell migration and invasion." (PMID 32824461, 2020). "As a novel member of IQGAPs family, a host of researches were conducted to explore the role of IQGAP3 in cancers." (PMID 31223291, 2019). "IQGAP3 was previously proved to be involved in cell proliferation, adhesion, migration and metastasis in different cancers." (PMID 31223291, 2019). "Considering the importance of IQGAP3 in cancers, in this study, we aimed to determine the biological role and molecular mechanism of IQGAP3 in HCC." (PMID 28810875, 2017). "Overall, we observed that while IQGAP3 was elevated in most cancer types at both mRNA and protein level, IQGAP2 was reduced in expression." (PMID 29073199, 2017). "As a scaffold protein, it is possible that IQGAP3 plays a critical role in the invasion and metastasis of cancer cells." (PMID 28810875, 2017). "On the other hand, IQGAP3 was consistently up-regulated across most of the cancer types including breast, lung, gastric, colorectal, brain, prostate, liver and kidney." (PMID 29073199, 2017). "We selected TCGA datasets of all eight cancers to study mutation and copy number change in IQGAP2 and IQGAP3." (PMID 29073199, 2017). "Most of the cancer types (lung, breast, prostate, brain, gastric, liver, kidney and colorectal) showed increased IQGAP3 mRNA expression." (PMID 29073199, 2017). "For both IQGAP2 and IQGAP3, a weak correlation was observed between promoter methylation and subsequent gene expression in all cancer types." (PMID 29073199, 2017).
cancer (continued). "IQGAP2 expression correlated positively with survivability, on the contrary, IQGAP3 expression levels correlated inversely with survivability, in most of the cancers." (PMID 29073199, 2017). "Previous studies have indicated that IQGAP3 plays an important role in cell proliferation, adhesion, migration, and metastasis in various cancers." (PMID 28810875, 2017). "To validate the in-silico analysis results we ascertained the expression and localization of IQGAP2 and IQGAP3 in cancer patients, using immunohistochemistry." (PMID 29073199, 2017). "The percentage of each type of IQGAP2 and IQGAP3 genetic alteration with cancer type has been summarised in S5 Table." (PMID 29073199, 2017). "So, we can conclude that observed upregulation of IQGAP3 can be attributed, atleast partly, to gene amplification in some cancers." (PMID 29073199, 2017). "The mRNA expression of IQGAP2 and IQGAP3 in individual cancers were analysed in two different publicly available databases viz." (PMID 29073199, 2017). "This will pave the way for using IQGAP2 and IQGAP3 as promising therapeutic targets and novel prognostic biomarkers for human carcinomas in the near future." (PMID 29073199, 2017). "IQGAP3 is located at 1q22, which is a hotspot for gene amplification in cancer and expressed in liver and intestines and other organs restrictively." (PMID 27390551, 2016). "The dysregulation of expression of IQGAP3 in cancer tissue suggests a potential role for this molecule in tumorigenesis." (PMID 24849319, 2014). "IQGAP3 is the latest addition to this family and its role in cancer development remains to be defined." (PMID 24849319, 2014). "Bioinformatics analysis shows that IQGAP3 is upregulated in multiple types of cancers, including ovary, lung, large intestine, gastric, bone marrow and breast malignancies." (PMID 24849319, 2014). "To investigate the functional consequence of upregulated IQGAP3 expression in cancer, we monitored changes in cell behavior following alteration of its expression level in cancer cell lines." (PMID 24849319, 2014). "Additionally, IQGAP3 has been identified as a crucial factor in stem cell regulation, being expressed in rapidly proliferating stem cells and cancer cells alike." (PMID 38674130, 2024). "Additionally, the validation of screened targeted small-molecule drugs will be conducted to enhance the potential utility of IQGAP3 as a biomarker for cancer immunity and prognosis." (PMID 38560572, 2024). "Each gene in the risk evaluator, PLXNA1, MARCKSL1, IQGAP3, PFN2, PON1, and TAK, has been reported to be associated with the prognosis or progression of cancer." (PMID 37954858, 2023). "Interestingly, IQGAP3 was highly expressed in both cancer and adjacent paired samples with (13 pairs of samples, Series: GSE66271) or without metastasis (14 pairs of samples, Series: GSE66270)." (PMID 36275458, 2022). "Amplification was the main reason for the mRNA of IQGAP3 to be upregulated in human cancer." (PMID 35274003, 2022). "High DNA methylation in IQGAP3 was correlated with better overall survival in human cancer types." (PMID 35274003, 2022). "Therefore, it is critical to investigate further the pan-cancer relationship of IQGAP3 expression with between TME." (PMID 36164370, 2022). "Prognostic importance of IQGAP3 CNVs in pan-cancer was analyzed using the GSCA database." (PMID 36164370, 2022). "We found that IQGAP3 expression was increased in different types of human cancer." (PMID 35274003, 2022). "We found that PTBP1 (an RNA-binding protein) could be a transcription factor of IQGAP3 in human cancer." (PMID 35274003, 2022). "The prognosis of IQGAP3 in pan-cancer analysis by using the prognostic database." (PMID 35274003, 2022). "Overall, these results demonstrated that PTBP1 may be a transcription factor for IQGAP3 in different cancer types." (PMID 35274003, 2022). "This study is the first multiomics analysis to explore the relation between IQGAP3 and pan-cancer." (PMID 36164370, 2022).
cancer (continued). "IQGAP3 plays a crucial part in the development and progression of several types of cancer." (PMID 35274003, 2022). "If IQGAP3 shows high expression in cancer, the miR expression in cancer should be low." (PMID 35274003, 2022). "We also analyzed the correlation between let-7c-5p and IQGAP3 in human cancers." (PMID 35274003, 2022). "PTBP1 was positively correlated with IQGAP3 expression in diverse cancer types." (PMID 35274003, 2022). "In addition, the low level of DNA methylation and high copy-number variation (CNV) of IQGAP3 significantly affected its expression in different types of cancer." (PMID 35274003, 2022). "PTBP1 expression was significantly positively corelated with IQGAP3 expression in human cancer." (PMID 35274003, 2022). "We wished to explore if an “IQGAP3 axis” plays an important part in cancer progression." (PMID 35274003, 2022). "Our results suggested that IQGAP3AR may be upstream of the lncRNA let-7c-5p, which regulates IQGAP3 expression in different cancer types." (PMID 35274003, 2022). "For molecular subtypes, IQGAP3 displayed different expressions in different cancer types." (PMID 35274003, 2022). "Therefore, a systematic analysis of IQGAP3 in pan-cancer was conducted based on multiomics data; here, IQGAP3 was determined as an effective prognostic molecular immune biomarker." (PMID 36164370, 2022). "Furthermore, IQGAP3 expression is associated with MSI, TMB, and immune cell infiltration in different cancer types." (PMID 36164370, 2022). "Let-7c-5p expression was negatively correlated with IQGAP3 expression in human cancers." (PMID 35274003, 2022). "Amplification was the main reason why the mRNA of IQGAP3 was upregulated in different cancer types." (PMID 35274003, 2022). "In addition, we identified a 3060-base pair (bp) long non-coding (lnc) RNA, termed “IQGAP3AR” (IQGAP3-associated lncRNA: ENSG00000234072), which showed high expression in human cancer that predicted a poor prognosis." (PMID 35274003, 2022). "We found that IQGAP3 expression was upregulated in different cancer cells lines." (PMID 35274003, 2022). "Clearly, these results indicated that to determine the prognosis of various cancers, IQGAP3 could be used as a biomarker." (PMID 36164370, 2022). "Analysis of the correlation between the DNA methylation of IQGAP3 and prognosis of cancer patients." (PMID 35274003, 2022). "Our study showed that IQGAP3 was highly expressed in 29 cancers." (PMID 36164370, 2022). "We examined IQGAP3 expression in lymph node metastasis of different types of cancer." (PMID 35274003, 2022). "Finally, we showed that the CNV of IQGAP3 in different cancer types was positively correlated with its expression." (PMID 35274003, 2022). "In addition, increased IQGAP3 promotes cell proliferation and invasion in breast cancer, and correlates with poor prognosis in various cancers based on a recent pan-cancer study." (PMID 32824461, 2020). "Interestingly, we observed the elevated expression of IQGAP3 from a very early stage of cancer progression (stage 1) and nodal metastasis (N0)." (PMID 32824461, 2020). "Positive IQGAP3 staining was observed mainly in the cancer cell nuclei." (PMID 33519444, 2020). "In other cancer types regulation of IQGAP3 levels can occur at transcriptional levels and beyond." (PMID 29073199, 2017). "To assess whether IQGAP3 affects cancer growth and prognosis in vivo, we investigated the orthotopic HCCLM3 hepatic tumors in nude mice." (PMID 28810875, 2017). "Hence, IQGAP2 and IQGAP3 have potential to be used as prognostic markers or therapeutic targets in specific cancers." (PMID 29073199, 2017). "However, only a few reports, in fewer sample size, are available which provide information regarding the expression pattern of IQGAP2 and IQGAP3 in different cancer types and their role in cancer development." (PMID 29073199, 2017). "We observed that high frequency of mutations were present in IQGAP3 promoter but not in IQGAP2 promoter in different cancers." (PMID 29073199, 2017).
cancer (continued). "Possibility of epigenetic regulation IQGAP3 expression, could not be established by our in-silico data, as we didn’t find any correlation between IQGAP3 expression and promoter methylation in cancers." (PMID 29073199, 2017). "In view of the potent impact of IQGAP3 expression on proliferation and migration of cancer cells cultured in vitro, we next sought to determine whether it also affected tumorigenesis in vivo using an established model of metastatic lung cancer." (PMID 24849319, 2014). "IQGAP3 is located at 1q21.3, which is a hotspot for gene amplification in cancer." (PMID 24849319, 2014). "Elevated levels of IQGAP3 protein were observed in 80 cancer tissues." (PMID 24849319, 2014). "The results detailed above suggested that IQGAP3 may have roles in cancer progression." (PMID 35274003, 2022). "Next, we investigated if IQGAP3 could act as a biomarker for different cancer types." (PMID 35274003, 2022). "IQGAP3 could serve as an effective prognostic biomarker for pan-cancer immune-related therapy." (PMID 36164370, 2022). "Our findings on the link between IQGAP3 expression and the abundance of immune cells, expression of immune checkpoint-related genes, and expression of proinflammatory moieties indicated that IQGAP3 has an indispensable role in regulation of the immune response in human cancer." (PMID 35274003, 2022). "Hence, IQGAP3 appears to have important roles in cancer progression and could be a promising biomarker." (PMID 35274003, 2022). "Furthermore, recent studies showed that IQGAP3 overexpression accelerates cell proliferation and invasion in several tumors, indicating it may play a role in cancer progression." (PMID 33519444, 2020). "Previous studies have shown that IQGAP3 may promote and accelerate cancer development in vitro." (PMID 33519444, 2020). "Indeed, IQGAP3 was found to bind to the Ras protein, which plays a role in cell cycle arrest, DNA repair, proliferation, and antiapoptosis in human cancers." (PMID 33519444, 2020). "Among them, only six genes—MMP11, ANGPTL1, GSTM5, IQGAP3, UHRF1, and CCBE1—were shared across all analyzed carcinomas." (PMID 39596491, 2024). "In this review, we summarize the different signaling pathways affected by IQGAP2 and IQGAP3, and the antithetic roles of IQGAP2 and IQGAP3 in different types of cancer." (PMID 36831467, 2023). "The common (pan-cancer) genes are MMP11 (+), C7 (-), ANGPTL1 (-), UBE2C (+), IQGAP3 (+) and ADH1B (-)." (PMID 36802377, 2023). "IQGAP3, as a member of the IQGAP family, promotes the proliferation, migration and invasiveness of cancer cells through interacting with its target proteins." (PMID 36168930, 2022). "IQGAP1 and IQGAP3 were significantly elevated in cancer tissues and considered oncogenic factors; whereas, IQGAP2 was significantly decreased in cancer tissues and was considered a cancer suppressor." (PMID 36320006, 2022). "We showed that IQGAP3 expression was positively correlated with TMB, MSI, immune cell infiltration, and immune modulators in diverse human cancers." (PMID 35274003, 2022). "High expression of IQGAP3 was positively correlated with the cell cycle, cell proliferation, DNA damage, DNA repair, EMT, and inflammation in different cancer types." (PMID 35274003, 2022). "IQGAP1 plays a role in cancer progression, whereas IQGAP2 seems to act as atumor suppressor, and IQGAP3 promotes cancer growth and metastases." (PMID 29581849, 2018). "IQ motif-containing GTPase activating protein 3 (IQGAP3), a primary member of the IQGAP family and GTPase-activating protein, is located at 1q21.3, which is a hotspot for gene amplification in cancer." (PMID 28810875, 2017). "Among the different cancer types and their respective sub-types, we mostly found reduced and elevated mRNA levels of IQGAP2 and IQGAP3, respectively, which coincided with poor survival rates of patients." (PMID 29073199, 2017).
cancer (continued). "The expression pattern and role of IQGAP1 has been well established in many cancers, whereas those of IQGAP2 and IQGAP3, have mostly remained unexplored." (PMID 29073199, 2017). "We examined the correlation between IQGAP3 expression and TMB of human cancers." (PMID 35274003, 2022). "We explored the correlation between IQGAP3 expression and MSI in human cancers." (PMID 35274003, 2022). "A high expression of IQGAP3 was positively correlated with the cell cycle (r = 0.74), cell proliferation (r = 0.62), DNA damage (r = 0.53), DNA repair (r = 0.39), EMT (r = 0.30) and inflammation (r = –0.30) in different cancer types." (PMID 35274003, 2022). "IQGAP3 was involved mainly in angiogenesis, apoptosis, cell cycle, cell differentiation, DNA damage, epithelial–mesenchymal transition (EMT), hypoxia, inflammation, invasion, metastasis, and proliferation in human cancers." (PMID 35274003, 2022). "IQGAP3 was involved mainly in angiogenesis, apoptosis, cell cycle, cell differentiation, DNA damage, EMT, hypoxia, inflammation, invasion, metastasis, and proliferation in human cancer." (PMID 35274003, 2022). "It would be interesting to prospect the opposing role of IQGAP2 in this particular cancer, wherein in-vitro studies could further help in identifying the role of IQGAP2 as a putative oncogene, along with IQGAP3." (PMID 29073199, 2017). "Determination of the precise roles of IQGAP3 in the pathogenesis and progression of HCC and activation of the TGF-β signaling pathway will help improve our understanding of the biological basis of cancer." (PMID 28810875, 2017). "The data reveal that IQGAP3 is one of the most essential molecules that connect the RAS and PI3K pathways, allowing them to influence each other and co-regulate functions farther down, and that this cross-talk contributes to the development and progression of cancer." (PMID 36831467, 2023). "However, the prognostic, upstream-regulatory, and immunological roles of IQGAP3 in human cancer types are not known." (PMID 35274003, 2022). "We found copy no. variation and mutations in specific cancers, for IQGAP2 and IQGAP3." (PMID 29073199, 2017). "However, the prognostic and immunological roles of IQGAP3 in human cancer are not known." (PMID 35274003, 2022). "None of the six genes (MMP11, ANGPTL1, GSTM5, IQGAP3, UHRF1, and CCBE1) have previously been categorized as carcinoma biomarkers collectively." (PMID 39596491, 2024).
urological diseases (1 paper, 2025). "CD24, TOP2A, IQGAP3, UBE2C, and CRH mRNA levels were also significantly higher in patients with NMIBC than in those with hematuria, which may indicate that they could be used as discriminative biomarkers for BCa detection compared to urological diseases." (PMID 40282460, 2025).
IQGAP3 also shares sentences with these, for which no sentence is quoted: gastric tumors (2 papers); Hematuria (2); lung squamous cell carcinoma (2); serous ovarian cancer (2); breast (1); colon adenocarcinoma (1); ductal breast carcinoma (1); gastric adenocarcinoma (1); gastric intestinal adenocarcinoma (1); Huntington disease (1); infection (1); invasive ductal breast carcinoma (1); invasive lobular breast carcinoma (1); leukemia (1); liver diseases (1); lymph node metastasis (1); medulloblastoma (1); melanoma (1); rectal adenocarcinoma (1); rectal mucinous adenocarcinoma (1); sarcoma (1); Skin Inflammatory Diseases (1); testicular germ cell tumor (1); uterine carcinosarcoma (1); Wilms' tumour (1).